CXCL1 (C-X-C motif chemokine ligand 1)
Diseases named in the same sentence as CXCL1 in open-access papers (continued):
Sharing a sentence is not in itself a finding about the gene and the disease.
tumor (continued). "This differential expression of CXCL1–3, 8–10, 12–14, and 16 in different immune cell types in HNSC suggests that they play an important role in the tumor microenvironment by affecting immune cells." (PMID 34247149, 2021). "CXCL1, an important ligand of CXCR2, which promotes cancer chemoresistance, progression and metastasis 54, recruits MDSCs to tumor site to induce immune suppression." (PMID 33897880, 2021). "Some of these changes are beneficial when it comes to non-tumor-promoting conditions, e.g., the decrease of VEGF, TGFβ, IL6, CXCL1, CXCL9, IL1β, and M2-macrophage-inducing IL4, as well as the increase of immuno-supportive and M1-associated IL12p70 and TNFα." (PMID 34064000, 2021). "These secretomes include CXCL1, CXCL5, 6 and 7, IL4, IL8, IL10, IL17b, S100A4, and EGF, which were also found to be involved in MSC migration to the tumour site." (PMID 34572431, 2021). "The considerable CXCL1-induced up-regulation of TLR4, TNFSF10/TRAIL, and KITLG expression along with MICA/MHCI down-regulation, enable tumor evasion from immune surveillance." (PMID 34195201, 2021). "For example, N-myc downstream regulated gene 1 (NDRG1)/Cap43 downregulates the expression of CXCL1, CXCL5, CXCL8, and VEGF in tumor cells, leading to the suppression of neutrophil infiltration." (PMID 34439836, 2021). "In castration-resistant prostate cancer, overexpression of CXCL1 promotes cancer cell epithelial-mesenchymal transition (EMT) and invasiveness, via AKT/NF-κB signaling pathway, thus favoring tumor progression." (PMID 34195201, 2021). "Additionally, the C-X-C motif chemokine ligand 1 (CXCL1) oncogene secreted by components of the tumor microenvironment is highly expressed in various cancer types, promoting tumor angiogenesis, migration, invasion metastasis, tumor progression, and chemoresistance." (PMID 34900673, 2021). "For instance, it was found that the chemokines C-X-C motif ligand 1, 2, 3, and 8 (CXCL1, CXCL2, CXCL3, and CXCL8) are overexpressed in melanomas, which is accompanied by increased proliferation of tumor cells and tumor metastasis." (PMID 34885171, 2021). "The result shows that in tumor cells, PMEPA1 were negatively correlated with some chemokines (including CXCL1, CXCL11, CXCL2, CXCL8, CX3CL1) and positively correlated with CXCL14 and LAG3." (PMID 34777336, 2021). "Deficient SLC7A2 drove MDSC recruitment by upregulation of expression CXCL1 through PI3K/Akt/NF-kκB pathway, thus avoiding immune surveillance and promoting tumor progression." (PMID 34108444, 2021). "MCs are recruited by several cancer cell-derived cytokines and chemokines (i.e., osteopontin, CXCL8, CCL2, CXCL1, and CXCL10) into TME and can directly interact with infiltrated immune cells, tumor cells, and ECM." (PMID 34337083, 2021). "Immunohistochemistry revealed that, in CXCL1+TNBCs, the cellular sources of CXCL1 included, in addition to CD133+BCSCs, tumor infiltrating immune cells, such as CD68+ macrophages, and the vast majority of BC cells." (PMID 34195201, 2021). "We also tested the impact of CXCL1/IL10/CCL4 on the colony forming ability of PC cells; this in vitro technique examines the capability of tumour cells to form large colonies." (PMID 34359731, 2021). "The same study further showed that the chemokines binding to CXCR2 (e.g., CXCL1 and CXCL2) were responsible for BM-neutrophils’ extravasation into the circulation and for their further migration into the tumor." (PMID 34680231, 2021). "Chemokines such as CXCL8, CXCR3, CXCL1, and CXCL5 regulate the tumor immune response in tumor microenvironment." (PMID 33955820, 2021). "CAFs in the primary tumor are able to express high levels of CXCL12, CXCL1, and insulin-like growth factor 1 (IGF1)." (PMID 34064859, 2021). "Several studies utilized genetically manipulated MSCs to deliver and express various anti-tumor agents, including type I interferon (IFN-α and IFN-β), CXCL1, IL-2, IL-12, cytokine deaminase, oncolytic virus, TRAIL and nanoparticles." (PMID 33472580, 2021).
tumor (continued). "In pancreatic cancer, mutant Kras drives release of CXCL1, 2 and 5, which are CXCR2 ligands necessary for angiogenesis, myeloid cell infiltration and tumor progression." (PMID 35127700, 2021). "We confirmed that TGFβ1 acted on tumor cells, causing a series of changes: upregulation of LAMC1; phosphorylation of NF‐κB; secretion of CXCL1; phosphorylation of STAT3 in CAF; and finally, the induction of the formation of iCAF, that is, tumor‐promoting CAF." (PMID 34218518, 2021). "The positive rate of CXCL1 staining was 81.6% (173 / 212) in COAD patients and 34.0% (16 / 47) in paracancerous non-tumor colon tissues." (PMID 34405013, 2021). "It is well known that tumor cells or stromal cells in the tumor microenvironment secrete chemokines such as C-C motif chemokine ligand 2 (CCL2), C-X-C motif chemokine ligand 1 (CXCL1), CXCL2, and CXCL5." (PMID 34209505, 2021). "MDSCs are recruited to tumor sites through GM-CSF; monocyte chemoattractant protein 1 (MCP1); CXCL1, 2, 5, and 12; IL-8; CSF1; prokineticin 2 (Prok2); CCL2; S100A8/9; and other factors derived from the TME47,61,62." (PMID 34403220, 2021). "Tumours from Osm−/− animals exhibited markedly reduced levels of several cytokines, including IL6, CXCL1, GM-CSF and TNFα, highlighting a profound change in the tumour environment." (PMID 34921158, 2021). "Given the relevance of the USP12-mediated chemokine, such as CXCL8, CXCL1 and CCL2, in tumour development and progression, we examined the mechanism underlying the USP12-mediated regulation." (PMID 34381028, 2021). "Furthermore, analysis of 366 HCC tumor samples from TCGA demonstrated positive associations of tissue CRP level and genes related to myeloid cells, including CD68 and CD14, as well as chemokines and receptors for the chemotaxis of monocytes or neutrophils, such as CCL2, CCR2, and CXCL1." (PMID 35070979, 2021). "As expected, we also saw CXCL1, CXCL8, CXCL10, CXCL11, CXCL13, and CXCL14 in tumor tissues were upregulated in the results of TCGA data and the difference was statistically significant (p < 0.05)." (PMID 34794429, 2021). "This was explained by the fact that CD14high tumor cells have a higher production of IL6, IL8/CXCL5, CXCL1, CXCL2, M-CSF, VEGF-A, FGF-2 than CD14low tumor cells." (PMID 34572939, 2021). "The pro‐inflammatory cytokine CXCL1/KC showed elevated expression in GBM with time, indicating the brain of the mice gradually changed to inflammatory state after tumor implantation." (PMID 34196474, 2021). "The results showed that the expression of CXCL1-2 and CXCL12 decreased with the development of tumor, while CXCL13 was opposite." (PMID 34123826, 2021). "Multiplex chemokine and cytokine quantification showed a marked decrease of the neutrophil chemoattractant CXCL1, IL6, and the tumor growth supporting TGFβ and VEGF in plasma-treated compared to untreated co-culture settings." (PMID 34064000, 2021). "The high expression of CXCL1/CXCL2 promoted the migration of myeloid cells and disrupted the accumulation of CD8+T cells in the tumor microenvironment, leading to accelerated tumor proliferation." (PMID 34630121, 2021). "TAMs secrete factors such as CCL22, CXCL1, and PDGF, which bind to corresponding receptors on tumor cells, thereby promoting tumor growth and metastasis, as well as resistance to various cancer treatments." (PMID 35070992, 2021). "CXCL1, CXCL5, and CXCL16 are able to facilitate tumor metastasis like lung cancer and gastric cancer." (PMID 34603309, 2021). "In the tumor stroma, CAFs secrete the cytokines CXCL1 and CXCL2 as well as the interleukin-6, which promote angiogenesis and tumor progression." (PMID 33806312, 2021).
tumor (continued). "Elevated levels of CXCL1 recruit CXCR2 positive MDSCs to the pre-metastatic liver tissue and promote tumour cell survival and metastasis while evading host immune responses." (PMID 33669775, 2021). "The chemokine receptor CXCR2 and its ligands CXCL1, CXCL2, CXCL3, CXCL5 and CXCL8 play critical roles in the chemoattraction of neutrophils towards tumor tissues." (PMID 34429454, 2021). "Therefore, CXCL1 neutralizing antibody or CXCR2 receptor inhibitors may represent the promising candidate drugs for Treg-mediated tumor immune escape and metastasis, which have received increasing research attention in recent years and are under preclinical or clinical trials." (PMID 34461944, 2021). "CXCL1 and CXCL2 chemokines strongly affect NDN and LDN migration, and tumor-conditioned media differently impact their chemotaxis." (PMID 34680231, 2021). "After data processing, we also found that the expression of CXCL1, CXCL10, CXCL11, CXCL13, and CXCL14 was significantly increased in tumor tissues, and the difference between CXCL10 was the most significant." (PMID 34794429, 2021). "Neoplastic cells producing chemokines (e.g. CXCL1), cytokines (TNF-α and IFN-γ) and adhesion proteins can also recruit neutrophilic granulocytes to the tumor microenvironment." (PMID 33146401, 2021). "The M-MDSC is attracted to tumor sites by CCL2, CCL5, and CSF1 and PMN-MDSC was attracted by CXCL1, CXCL5, CXCL6, CXCL8, and CXCL12." (PMID 34858479, 2021). "Based on the literature, these chemokines can be produced by immune cells; however, there is evidence that CXCL1, CXCL10, and IL-8 can be produced by tumor and stromal cells." (PMID 34072037, 2021). "In colitis-associated colon cancer, the source of CXCL1 in hypoxia may be tumor epithelial cells which, in a reaction mediated by HIF-2, increase the expression of this chemokine in the tumor microenvironment resulting in the recruitment of monocytes to the tumor niche." (PMID 33467722, 2021). "Studies have shown that the high expression of inflammatory chemokines ligand 1 (CXCL1) and ligand 2 (CXCL2) is closely related to tumor invasion, metastasis and poor prognosis." (PMID 34630121, 2021). "The expression levels of CXCL1/KC in the brain and serum of GBM bearing mice were evaluated based on time after tumor implantations." (PMID 34196474, 2021). "Tumor cell migration to metastatic lesions is promoted through MSC secretion of chemoattractants, such as CXCL1, CCL5, CXCL5, CXCL8 and CXCL7." (PMID 33472580, 2021). "It has been shown that certain tumours produce chemotactic agents, such as TNFα; IL‐17; CXCR2 ligands CXCL1, CXCL2, CXCL5, and CXCL6, to attract neutrophils." (PMID 33665979, 2021). "CXCL1 is an inflammatory chemokine secreted mainly by CRC epithelia and myofibroblasts and is capable of driving tumor initiation and progression." (PMID 34670584, 2021). "In agreement, shRNA-mediated of CCL20, CXCL1, or TFF1 depletion in CFPAC-1 pancreatic cancer cells significantly decreased the percentage of macrophages that interact with tumor cells in vivo, while IL-8 depletion reduced CD31+ endothelial cell recruitment." (PMID 32373132, 2020). "In parallel, CXCL1 arriving from TAMs was found to promote the CD44+/CD24− sub-population and formation of tumor spheroids in human TNBC cells." (PMID 32582148, 2020). "Among the chemokine ligands, CXCL1, CXCL2, CXCL6, and CXCL9 genes also displayed a higher expression in tumors with BD3 compared to low-grade tumor budding." (PMID 32719800, 2020).
tumor (continued). "To gain further insight on the molecular mechanism mediating gMDSC recruitment to BCM-2277 tumors, we then treated a cohort of tumor-bearing mice with an inhibitor of CXCR2, the receptor through which CXCL1 and CXCL2 signal." (PMID 32634121, 2020). "This resulted in the expression of the pro-inflammatory cytokines and chemokines CCL20, CXCL1, IL-8, and TFF1 leading to the recruitment of macrophages in the tumor microenvironment and of vasculogenic endothelial cells to promote angiogenesis." (PMID 32373132, 2020). "Recent observations have shown that the chemokine CXCL1 and its receptor CXCR2 assist with the homing of neutrophils into the tumor microenvironment." (PMID 32079335, 2020). "Prior studies have described the role of CXCL1 as an integral chemokine ligand that regulates the EMT transition by regulating the crosstalk between cancer cells and tumor microenvironment." (PMID 33126568, 2020). "In contrast, increased serum levels of chemokines CXCL1 and CXCL2 in mice correlated with increasing levels of CXCR2-expressing neutrophils in the blood and enhanced melanoma growth, with tumor growth being reduced by antibody-mediated blocking of CXCR2." (PMID 33105656, 2020). "IL-17 not only enhances tumor-infiltrating MDSCs, probably by increasing CXCL1 and CXCL5 secretion by tumor cells, but also potentiates their inhibition on T cells through upregulation of ARG1 and IDO." (PMID 32793192, 2020). "The attracted neutrophils expressed CXCL1 and CXCL8, MMP-2 and MMP-9, thereby inducing tumor angiogenesis and subsequent tumor progression and metastasis." (PMID 32422991, 2020). "TPL2 signaling can further interfere with lymphocyte-mediated anti-tumor immunity by enhancing the infiltration of immunosuppressive cells such as Treg cells and MDSCs through the induction of CCL22, CXCL1 and CXCL2 94-96." (PMID 32724474, 2020). "Before RT, the only protein expressed in the tumor-free lung of the RP-G1 patient was ICAM while the tumor-free lung of the RP-G3 patient presented an overexpression of CD154, CXCL-1, ICAM, IFN-γ, IL-1ra, IL-23, MIF and PAI-1." (PMID 33109238, 2020). "IL-17 induces the secretion of CCL2, CXCL1, CXCL5, CXCL6, and CXCL8 from several types of cells that infiltrate the tumor, and subsequently, it recruits myeloid-derived suppressor cells, including tumor-associated macrophages." (PMID 32756356, 2020). "In fact, neutrophils extravasate the blood and recruit into tumor tissue in response to cytokines (IFN-γ and TNF-α), chemokines (KC/CXCL1 and MIP2α/CXCL2 in mice) and cell adhesion molecules (i.e., CD11b)." (PMID 32499786, 2020). "CXCR2 promotes the process of metastasogenesis and tumor growth, while the two chemokines that bind to CXCR2 (CXCL1 and CXCL5) are released by macrophages, and this process is supported by GC cells." (PMID 33182840, 2020). "The expression of STC2, ESM1, INHBA, CXCL1 and TDGF1 was significantly increased in tumor tissues than in normal tissues, whereas GLP2R expression was higher in normal tissues than in tumor tissues." (PMID 32788867, 2020). "CXCR2 is a receptor for CXCL1, 2, and 3, and IL8 that has been shown to have a profound effect on tumor epithelial interactions with stromal cells." (PMID 33520697, 2020). "CXCL8 and CXCL1 belong to the CXC chemokine family, which acts as an important multifunctional cytokine to modulate tumour proliferation, invasion and migration in an autocrine or paracrine manner." (PMID 32730361, 2020). "Measurements of 36 different chemokines in the culture medium revealed a significant decrease in the secretion of CCL5, CCL8, CXCL1, CXCL2, CXCL5, and TGFβ1 and a significant increase in TGFβ2 secretion by TB9-Fhit transfected tumor cells." (PMID 32545680, 2020). "Chemokine CXCL1 is a monomeric protein of chemotaxis cytokines, which specifically binds to its receptor CXCR2 and has been reported to promote tumor growth and metastasis in various cancers." (PMID 33223508, 2020).
tumor (continued). "Hypoxia induced expression of CXCL1 (GRO-α), CXCL2 (MIP2α), CXCL5 (LIX) recruited anti-tumor neutrophils, which inhibited tumor growth by inducing tumor cell detachment from the basement membrane." (PMID 33262763, 2020). "Macrophages are attracted to tumor sites expressing chemotactic factors such as CCL2, CCL5, CCL7, CCL8, CXCL1, and CXCL12." (PMID 31991604, 2020). "RT increased cytokine response of the most overexpressed proteins in the tumor and tumor-free lungs of the RP-G3 patient, with a higher expression of CD154, CXCL1, IL-1ra, IFN-γ, IL-23 and PAI-1." (PMID 33109238, 2020). "CXCL1 expression in the KPC system also depends on the necrosome, and in a study of KPC orthotopic tumors, RIP-1/RIP-3 driven necroptosis upregulates tumor-derived CXCL1 production and enhances peritumoral MDSC infiltration." (PMID 33304355, 2020). "With the regulation of the tumor microenvironment, more genes were upregulated with over two-fold differences in both HK1 and C17 xenografts after CYLD knockout, including BCL2A1, CXCL1, BIRC3, SERPINB2, total VEGF, TNFA, and VEGFA." (PMID 32708712, 2020). "With this aim, several groups have explored the generation of synthetic TILs expressing chemokine receptors for different chemokines secreted by tumor cells, such as CXCR2, which is the receptor for several chemokines such as CXCL1 and CXCL8." (PMID 33680923, 2020). "Some of these chemokines are involved in the recruitment of cells into the tumor niche: CCL2/MCP-1 in the recruitment of TAMs, and CXCL1/GRO-α in the recruitment of neutrophils and myeloid-derived suppressor cells (MDSC)." (PMID 33114763, 2020). "Reversely, the chemokine receptor CXCR2 and its ligands CXCL1, CXCL2, and CXCL5 play an important role in homing of neutrophils to cancer cells to limit tumor growth." (PMID 33105656, 2020). "The tumor tissues isolated from those nude mice were further immunized with four antibodies: DACH1, CXCL1, cyclin D1, Ki67." (PMID 31998654, 2019). "In mouse model of CRC, ablation of IL-17 resulted in reduced levels of CXCL1 and CXCL2, which correlates with decreased numbers of tumor infiltrating myeloid cells." (PMID 31775909, 2019). "The chemokines CXCL1, CXCL2, CXCL5, CXCL6, and CXCL8 secreted from tumor cells attract neutrophils in the blood to the tumor microenvironment via CXCR1 and CXCR2 on the surface of neutrophils." (PMID 30736371, 2019). "CXCL1 and CXCL2 gradients are found in tumor-bearing mice, low level of chemokine is found in bone marrow (BM) and high level in the tumor." (PMID 31799175, 2019). "Colon inflammation contributes to colorectal cancer development, by modulating the expression in tumor lesions of cytokines such as TNFα and IL6 and chemokines, i.e., CXCL1, prostaglandins, COX-2, and Wnt5A (Wnt Family Member 5A)." (PMID 31799175, 2019). "The recruited neutrophils present high expression of tumor-promoting genes such as TNF-α, CXCL1, MMP9, and VEGF." (PMID 31474975, 2019). "Of note, CXCL1 and LCN2 synergistically enhance tumor malignancy, indicated by the profound promotion of DU145 migration that occurs from the stimulation with both cytokines." (PMID 31500632, 2019). "Chemotactic cytokines released from a tumor microenvironment i.e. CCL2, CXCL1, CXCL10, PGE2, histamine, VEGF, angiopoietin 1 (Ang1), CXCL8/IL-8 attract mast cells from the vicinity and recruit them from circulation." (PMID 30680411, 2019). "Consistent with pathological features, there was significantly higher expression of cytokines IL-6 (Il6) and TNFα (Tnfa), chemokines KC (Cxcl1), MIP2 (Cxcl2), and MCP1 (Ccl2), and tumor-promoting molecule COX2 (Cox2) in Nlrp12-/- HCC." (PMID 30990169, 2019). "A number of studies have indicated the functional role of chemokines, including CXCL1 and CXCL8, in the tumour microenvironment." (PMID 31147602, 2019).